ALB (albumin)
Diseases named in the same sentence as ALB in open-access papers (continued):
Sharing a sentence is not in itself a finding about the gene and the disease.
Sepsis (continued). "While there is consistent evidence of the consequences of albumin oxidation in patients with cirrhosis or decompensated hepatic failure, the literature describing the oxidation status of albumin in sepsis is scant." (PMID 34447316, 2021). "Oxidative damage subsequently impairs the binding properties of albumin as found in healthy and diseased subjects, including patients with cirrhosis of the liver, kidney disease, and sepsis." (PMID 33925831, 2021). "Our results also showed a significant association between previously well-known risk factors for mortality in sepsis and especially risk factors for mortality in CDI, such as age, albumin levels, and AKI, thus confirming the validity of our results." (PMID 34209348, 2021). "Based on data from the MIMIC III database, this study aims to further clarify the effect of hypoproteinemia on the prognosis of sepsis patients and the necessity of exogenous albumin supplementation." (PMID 34934165, 2021). "On day 1, HMA concentrations in sepsis patients were significantly reduced in albumin and crystalloids groups compared to healthy controls and to a similar extent." (PMID 34447316, 2021). "Although albumin has various physiological effects, the benefits of albumin supplementation in sepsis patients need to be carefully evaluated." (PMID 34934165, 2021). "Increased hospital length of stay was associated with older age, higher BMI, chronic steroid use, preoperative sepsis, and lower albumin." (PMID 34123604, 2021). "The sepsis patients were randomized (1:1) to treatment with 20% albumin and crystalloid solution or crystalloid solution alone." (PMID 34447316, 2021). "We found that albumin was most utilized for sepsis and septic shock, hypovolemia and hypotension, and intradialytic hypotension in our community hospital setting and it was ordered by critical care, nephrology, and surgery departments." (PMID 34613990, 2021). "An isolated substitution of albumin in the course of infection, especially in sepsis, is controversially discussed; however, studies have shown that reduced albumin levels are associated with an increased risk of orthopedic wound infections." (PMID 32424439, 2021). "As regard the role of albumin, some studies reported that albumin is an important factor affecting the critical prognosis of patients with sepsis/septic shock." (PMID 34015023, 2021). "The objective of the study was to evaluate the effect of hypoproteinemia on the prognosis of sepsis patients and the effectiveness of exogenous albumin supplementation." (PMID 34934165, 2021). "Subgroup analysis using sepsis risk factors is also performed: serum WBC, urine culture, and albumin-globulin ratio (AGR)." (PMID 33954204, 2021). "Admission values of se-creatinine, u-TP, u-albumin, and u-actin/u-creatinine were significantly higher (p<0.05) in the septic and sepsis-related AKI groups compared with the control patients." (PMID 34310652, 2021). "The lactate/albumin ratio was reported to be correlated with short-term mortality in patients with sepsis or septic shock." (PMID 34943582, 2021). "Initial conservative treatment is always required to optimize the general health of the patients by correcting nutritional status, replacement of fluid and electrolytes, improvement of serum albumin and transferrin and most importantly to control sepsis." (PMID 34040778, 2021). "This study was conducted to investigate the predictive role of C-reactive protein-to-albumin ratio (CAR) for sepsis and prognosis in severe burns." (PMID 33833617, 2021). "We found that albumin was most utilized for sepsis and septic shock, hypovolemia and hypotension, and intradialytic hypotension in our community hospital setting and it was most frequently ordered by critical care, nephrology, and surgical departments." (PMID 34613990, 2021). "In this study, we investigated the relationship between albumin oxidation and sepsis severity in a selected cohort of patients from the Albumin Italian Outcome Study (ALBIOS)." (PMID 34447316, 2021).
Sepsis (continued). "This was a retrospective analysis of a multicenter randomized clinical trial on albumin replacement in severe sepsis or septic shock (the Albumin Italian Outcome Sepsis Trial, ALBIOS)." (PMID 33741039, 2021). "Despite various physiological effects of albumin, the benefits of albumin supplementation in sepsis patients need to be evaluated with caution." (PMID 34934165, 2021). "The therapeutic efficacy of serum albumin in sepsis and cirrhosis also demonstrates its essential role in modulating inflammation, oxidative stress, and the plasma volume expansion." (PMID 34122505, 2021). "Previous studies have investigated the lactate/albumin ratio (L/A) as a biomarker in sepsis and septic shock; however, they were either retrospective or small in sample size." (PMID 34854770, 2021). "The L/A ratio has been proposed as a marker for combined interpretation of lactate and albumin levels; some studies have investigated its usefulness as a prognostic marker in sepsis or ICU patients." (PMID 34691782, 2021). "Albumin has been previously studied in sepsis and is even included in the APACHE II score commonly used to predict mortality in critically ill patients." (PMID 34854770, 2021). "There is emerging evidence on the role of C-reactive protein to albumin ratio (C-reactive protein/Albumin) in predicting outcomes in patients with critical illness and sepsis, admitted to intensive care unit." (PMID 35199783, 2021). "Patients with severe sepsis were randomized to receive either 20% albumin and crystalloids or crystalloids alone after initial early goal-directed resuscitation." (PMID 32449147, 2020). "With respect to laboratory data before treatment, platelet count and serum albumin level were significantly lower in the sepsis group than in the non-sepsis group (p = 0.001 and p = 0.016, respectively)." (PMID 32160878, 2020). "Rather, albumin is best viewed as an acute phase reactant that decreases predictably in critical illness such as sepsis." (PMID 32582446, 2020). "Albumin concentration was selected in the final model as a parameter reflecting the severity of sepsis." (PMID 32301057, 2020). "Although the beneficial effects of rhTM, used in clinical conditions, remains controversial, rhTM treatment is known to decrease administration of albumin in patients with severe sepsis‐induced DIC (Hagiwara, Tanaka, Uemura, Matsuda, & Kimura, 2016)." (PMID 32497259, 2020). "As such, we cannot comment about the prognostic value of the lactate to albumin ratio in predicting the progression rate from sepsis to septic shock." (PMID 33072780, 2020). "Albumin (Alb), a well-established traditional nutritional and inflammatory biomarker, is shown to be a prognostic biomarker in patients with sepsis." (PMID 32454793, 2020). "We found that SIRT1 was associated with ameliorated inflammation and disease severity (reflected by the correlation of SIRT1 with Scr, WBC, CRP, SOFA score, APACHE II score, and albumin) in sepsis patients." (PMID 33263643, 2020). "This indicated that iso-oncotic albumin helps with providing more volume for sepsis resuscitation, while hyperoncotic albumin is more beneficial for uncorrected blood loss patients with normal vascular permeability." (PMID 33317590, 2020). "As such, the incorporation of albumin as a reflection of nutritional status in the L/A ratio increases its use in prognostication of sepsis patients." (PMID 33072780, 2020). "Nevertheless, there was a tendency for a potential survival benefit of albumin therapy in patients who started therapy 6–24 h after onset of sepsis compared to those who started it earlier." (PMID 33287911, 2020). "Among patients with sepsis and surgery, balanced crystalloids and albumin achieved better survival, fewer acute kidney injury, and smaller blood transfusion volumes than saline and L-HES." (PMID 33317590, 2020).
Sepsis (continued). "It is now well accepted that, besides a role in maintaining colloidal osmotic pressure, albumin has secondary functions that are critical to normalizing many of the inflammatory pathways involved in sepsis." (PMID 32819439, 2020). "A low baseline glutamine level was associated with biochemical markers of sepsis (higher CRP and lower albumin values) and injury severity (higher APACHE II and SOFA scores)." (PMID 32028696, 2020). "Low levels of albumin and high levels of sepsis-related biomarkers, including the C-reactive protein and lactate, were also significant risk factors for mortality." (PMID 33267829, 2020). "Please note that there is a clear relationship between albumin concentration and the presence of sepsis among patients." (PMID 32301057, 2020). "Among sepsis and surgical patients, balanced crystalloids and albumin attained lower mortality rates, lower risks of acute kidney injury, and less red blood transfusion volume than did saline and L-HES." (PMID 33317590, 2020). "The CRP to albumin (CRP/Alb) ratio has recently been considered a more useful indicator of sepsis than CRP or albumin alone." (PMID 33324592, 2020). "Although the survival rates in the two groups were similar, a post hoc analysis of 1218 patients with severe sepsis showed decreased mortality in the albumin group compared to patients treated with 0.9% saline solution alone." (PMID 33287911, 2020). "Platelet count and serum albumin level were significantly lower in the sepsis group than in the non-sepsis group (p = 0.001 and p = 0.016, respectively)." (PMID 32160878, 2020). "Fleck’s group has demonstrated an elevated albumin transcapillary escape rate in patients with either sepsis or cancer." (PMID 32982584, 2020). "Scr (P < .001), WBC (P = .019), and CRP (P < .001) were increased, while albumin (P < .001) was decreased in sepsis patients compared with healthy controls." (PMID 32309886, 2020). "High respiration frequency, high pulse rate, and low plasma albumin are the most important predictors of sepsis." (PMID 32737308, 2020). "The CRP/albumin ratio has been already identified as a prognostic biomarker to assess outcomes in patients with sepsis, cancer, and chronic inflammatory diseases." (PMID 32344777, 2020). "Age, male, sepsis, albumin, lymphocyte count, Hb, creatinine, HbA1c and ISTH overt DIC on admission were identified as risk factors that were independent of disease severity for PIICS in surviving patients." (PMID 32824569, 2020). "There are existing controversies to consider albumin as a supplementary treatment for liver and renal failure as well as volume resuscitation in sepsis." (PMID 32776978, 2020). "As an acute-phase protein, albumin (ALB) usually negatively responds to surgical stress, injury or sepsis." (PMID 33585551, 2020). "Mean serum albumin and Apo-A1 concentrations were significantly lower in dogs with sepsis compared to healthy ones, while mean serum CRP concentrations were above the reference interval in the entire population of septic dogs." (PMID 32478112, 2020). "This evidence led to the weak recommendation and low quality of evidence for using albumin in addition to crystalloids in the initial resuscitation of sepsis and septic shock in the surviving sepsis guidelines." (PMID 32819439, 2020). "The administration of dexmedetomidine significantly improved CRP, PCT, and ALB levels in patients with sepsis requiring mechanical ventilation." (PMID 32778146, 2020). "Several systematic meta-analyses of albumin therapy in sepsis or septic shock have shown trends toward 90-day reductions in mortality associated with septic shock, especially when administered within 6 h." (PMID 32819439, 2020). "SIRT1 negatively correlated with Scr (r=-0.236), WBC (r=-0.202), and CRP (r=-0.405) and positively correlated with albumin (r=0.416) in sepsis patients." (PMID 33263643, 2020).
Sepsis (continued). "Albumin is of benefit in patients with sepsis owing to its scavenging, anti-oxidant as well as endothelial stabilizing effect apart from its additional benefit of volume expansion." (PMID 32704299, 2020). "In the multivariate Cox proportional regression (adjusted for age, presence of HF and COPD, serum albumin, Na and phosphorus), AF was significantly associated with overall cardiovascular death, death due to AMI/ CAD and sepsis." (PMID 31999778, 2020). "The levels of laboratory indices, including white blood cell count, hemoglobin, hematocrit, platelet count, albumin, aspartate aminotransferase, and creatinine, were significantly worse in the sepsis patients compared to those seen in healthy controls." (PMID 32922168, 2020). "Here, we determined the role of hepatocyte AMPKα1 in sepsis by using hepatocyte-specific AMPKα1 knockout mice (H-AMPKα1 KO) generated with Cre-recombinase expression under the control of the albumin promoter." (PMID 32117320, 2020). "In sepsis, the degraded glycocalyx layer becomes thinner and more sparse, allowing plasma proteins (e.g., albumin) and fluid to move across the vascular wall, leading to tissue edema formation." (PMID 30654825, 2019). "The CKD-with-sepsis group showed the lowest kidney function, urine volume, and serum glucose and albumin levels." (PMID 31795376, 2019). "In experimental sepsis and shock resuscitation, hyper-oncotic albumin showed anti-inflammatory and antioxidant properties, thus minimizing lung injury." (PMID 31311539, 2019). "The serum levels of Scr, WBC, CRP and PCT were higher in sepsis patients than that in healthy controls, whereas the serum albumin level was lower in patients group, and all differences reached significant levels (all P < 0.001)." (PMID 31771650, 2019). "We did not identify clinical studies that investigated the utility of albumin administration in preventing glycocalyx degradation in sepsis." (PMID 30654825, 2019). "For examples, patients with sepsis or septic shock had higher value of CRP/ALB ratio as a cut-off value than in our study." (PMID 29495423, 2018). "A reanalysis of the ALBIOS trial suggested that patients with septic shock - defined by vasopressor-dependent hypotension in the presence of severe sepsis (Shock-2) - had a survival benefit when treated with albumin." (PMID 30261898, 2018). "The CRP/albumin ratio was initially developed to predict clinical outcome and complications in patients with severe medical illness, such as sepsis; after that, it was also indicated to predict prognosis in some cancer patients." (PMID 30258731, 2018). "We suggest against the routine use of albumin solution during the initial resuscitation of patients with sepsis (2C)." (PMID 29435330, 2018). "The reduction in serum albumin levels in sepsis is due in part to increased microvascular permeability/capillary leak." (PMID 29488356, 2018). "Kidney immunohistochemistry revealed significantly increased levels of nitrotyrosine and extravasated albumin in sepsis, concomitant with reduced CSE and PGC1α expression." (PMID 30343340, 2018). "In that study, the cut-off value for the CRP/albumin ratio as predictor of mortality was 5.09 in patients with severe sepsis or septic shock." (PMID 30297655, 2018). "There were 10 common non-renal variables that were reported in more than three prediction models: mechanical ventilation, age, gender, hypotension, liver failure, oliguria, sepsis/septic shock, low albumin, consciousness and low platelet count." (PMID 28056039, 2017). "Systemic inflammation, such as sepsis, leads to endothelial dysfunction, which in turn increases paracellular permeability and outflow of albumin/fluid into the interstitial space." (PMID 29058634, 2017). "Electrolyte concentrations and buffer constituents of resuscitation fluids can modulate hepatic cytokine production and leukocyte recruitment in septic mice, while the effects of albumin are modest during early sepsis." (PMID 28105603, 2017).
Sepsis (continued). "Six met criteria for sepsis; serum albumin fell to <3.5 g/dL, consistent with serious bacterial infection, in 73 (81%) of the 90 patients." (PMID 28726607, 2017). "We recently reported a reduced zinc binding capacity in a porcine model of sepsis when zinc was added to the serum samples due to the downregulation of albumin, the major zinc binding protein in serum." (PMID 28472045, 2017). "Given that convective transport of albumin occurs through these pores, it is possible that convective transport of albumin due to a transiently increased transcapillary hydrostatic pressure during the distribution of crystalloids is larger in sepsis." (PMID 29075932, 2017). "Among 9 recipients with both high CRP and low albumin levels, 4 recipients had neutrophil counts equal to or exceeding 500/μl at the onset of bacteremia, and 8 recipients had severe sepsis or septic shock." (PMID 28938875, 2017). "In a previous study, pre-replacement of albumin during severe sepsis had an advantage of controlling the mean arterial pressure to fill the intravascular compartment and to remove the nitric oxide contributing to peripheral vasodilatation." (PMID 28723973, 2017). "To further assess any effects of albumin on hepatic inflammation, we measured hepatic concentrations of various pro- and anti-inflammatory cytokines relevant in sepsis." (PMID 28105603, 2017). "Sepsis, for instance, can influence synthesis, consumption, and distribution of albumin between intra and extravascular compartments." (PMID 28344803, 2017). "The objective of the present study was to investigate if the use of dextran-70 in addition to albumin and crystalloids influences organ failure or mortality in patients with severe sepsis or septic shock." (PMID 28683810, 2017). "We found urine albumin to be associated with PDA and PDA size also when adjusted for gestational age, gender, and sepsis." (PMID 28068947, 2017). "The Surviving Sepsis Campaign guidelines currently recommend crystalloids as first-line therapy and colloid solutions containing albumin when excessive fluid resuscitation is required." (PMID 28105603, 2017). "In this study, we have shown that fluid resuscitation with albumin has minimal effects on hepatic leukocyte recruitment in a murine model of early sepsis." (PMID 28105603, 2017). "Taken together, this provides a rational for the study of alternatives to albumin in patients with sepsis requiring large amounts of fluid." (PMID 28683810, 2017). "Our study shows that the lactate/albumin ratio at admission can be used as an independent predictor of mortality in patients with severe sepsis or septic shock." (PMID 28869492, 2017). "We also evaluated some clinical parameters associated AGI, such as AGI type (primary or secondary), GI surgery, serum albumin, sepsis, serum C-reactive protein, serum procalcitonin, arterial lactate, catecholamine support, SOFA score, APACHE II score, and IAP." (PMID 28356059, 2017). "The CRP/ALB ratio was primarily investigated for the purpose of predicting mortality in patients with sepsis." (PMID 27812440, 2016). "Given the cost of albumin and safety issues related to some other colloids, the sepsis resuscitation fluid debate has moved toward identifying the optimal crystalloid choice for use in sepsis." (PMID 27081589, 2016). "For patient type 3 who needs volume expansion for resuscitation in sepsis, crystalloid was, again, the first-choice of fluids (62–82 %), followed by 5 % albumin (4–17 %)." (PMID 27313844, 2016). "As albumin is synthesized in the liver, patients with liver dysfunction, such as cirrhosis and sepsis, have lower levels of albumin, which favors increased serum free fatty acid." (PMID 27078880, 2016). "After that, the mixed bacteria in the intestinal contents constantly enter into the abdominal cavity to induce the infection of the abdominal cavity, which would result in endotoxemia or sepsis, and eventually initiate pulmonary albumin leakage to trigger ALI." (PMID 27413385, 2016).